TIGIT (T cell immunoreceptor with Ig and ITIM domains)
Description:
Inhibitory receptor that plays a role in the modulation of immune responses. Suppresses T-cell activation by promoting the generation of mature immunoregulatory dendritic cells. Upon binding to its ligands PVR/CD155 or NECTIN2/CD112, which are expressed on antigen-presenting cells, sends inhibitory signals to the T-cell or NK cell. Mechanistically, interaction with ligand leads to phosphorylation of the cytoplasmic tail by Src family tyrosine kinases such as FYN or LCK, allowing subsequent binding to adapter GRB2 and SHIP1/INPP5D. In turn, inhibits PI3K and MAPK signaling cascades. In addition, associates with beta-arrestin-2/ARRB2 to recruit SHIP1/INPP5D that suppresses autoubiquitination of TRAF6 and subsequently inhibits NF-kappa-B signaling pathway. Also acts as a receptor for NECTIN4 to inhibit NK cell cytotoxicity.
Synonyms: VSIG9; VSTM3; FLJ39873; DKFZp667A205; WUCAM
Tractability: Antibody: a drug acting on it is in phase 2 or 3 trials; UniProt places it where antibodies can reach, with high confidence; its Gene Ontology location is reachable by antibodies, with high confidence; UniProt predicts a signal peptide or a membrane-spanning region. Other modalities: a drug acting on it is in phase 1 trials.
Gene: Protein-coding gene on chromosome 3 (114,276,913 to 114,310,288, forward strand). Ensembl gene ENSG00000181847.
Subcellular location: Cell membrane
Gene Ontology:
Molecular function: identical protein binding; protein binding; signaling receptor activity; signaling receptor binding
Biological process: negative regulation of interleukin-12 production; negative regulation of natural killer cell mediated cytotoxicity; negative regulation of T cell activation; positive regulation of interleukin-10 production
Cellular component: cell surface; plasma membrane
Genetic constraint (gnomAD): Loss-of-function variants: 10 observed, 18.25 expected, observed/expected ratio (o/e) 0.55, 90% interval 0.34 to 0.93. The upper end of that interval is the gene's LOEUF score, 0.93, which puts it in group 3 of 6, group 1 being the genes least tolerant of losing a copy. Missense variants: 289 observed, 306.29 expected, observed/expected ratio (o/e) 0.94, 90% interval 0.86 to 1.04. Synonymous variants: 130 observed, 127.57 expected, observed/expected ratio (o/e) 1.02, 90% interval 0.88 to 1.18.
Homologues: Orthologues: chimpanzee TIGIT (98% identical), macaque TIGIT (88% identical), rabbit TIGIT (73% identical), pig TIGIT (68% identical), dog TIGIT (67% identical), mouse Tigit (59% identical), rat Tigit (57% identical), zebrafish si:ch73-22o12.1 (16% identical), zebrafish pvrl2l (15% identical), zebrafish si:ch211-222f23.6 (14% identical), zebrafish zgc:113337 (14% identical), zebrafish si:ch211-141e20.2 (14% identical), and 4 more. Paralogues in human: NECTIN4 (20% identical), CD226 (19% identical), NECTIN2 (18% identical), CADM2 (17% identical), CADM1 (16% identical), CADM3 (16% identical), NECTIN1 (16% identical), PVR (16% identical), NECTIN3 (14% identical), CADM4 (14% identical), CD200 (14% identical), CRTAM (13% identical), and 2 more.
Diseases named in the same sentence as TIGIT in open-access papers:
TIGIT is named in the same sentence as 256 diseases in open-access papers, as found by Europe PMC text mining. Sharing a sentence is not in itself a finding about the gene and the disease. The quoted sentences say what the papers report.
melanoma (171 papers, 2015 to 2026). A malignant, usually aggressive tumor composed of atypical, neoplastic melanocytes. "Human DC2/moDC and TAM signatures were generated based on our scRNAseq and correlated with three Treg-associated genes (i.e., FOXP3, CTLA4, and TIGIT) in patients undergoing RT of radioresistant tumors (i.e., melanoma, glioblastoma, and head and neck cancer)." (PMID 40146036, 2025). "TIGIT expression can be closely associated with melanoma occurrence, development, and prognosis; consequently, decreased TIGIT expression is associated with inhibited tumor growth in melanoma patients." (PMID 38732242, 2024). "TIGIT+ NK cells exhibited lower killing activity against CD155+ MHC class-I deficient melanoma FO-I as compared with TIGIT− NK cells." (PMID 38543173, 2024). "In contrast to the association of high CD47 and TIGIT with increased survival in melanoma, it is notable that the opposite was recently reported for lung squamous cell carcinoma." (PMID 36768931, 2023). "Upregulated TIGIT expression has been associated with poor prognosis of multiple cancers such as gastric cancer, melanoma and hepatocellular carcinoma (HCC)." (PMID 37799715, 2023). "In a B16F10 melanoma model, transfer of TIGIT-deficient Tregs along with wild-type CD4+ and CD8+ T effector cells into tumor-bearing Rag mice has also been shown to markedly curtail tumor growth." (PMID 37291608, 2023). "TIGIT-deficient mice show significantly delayed tumour growth in distinct murine models; however, the number of pulmonary metastatic deposits was comparable following B16 melanoma cell inoculation in TIGIT-deficient and wild-type mice." (PMID 37325585, 2023). "TIGIT expression in TILs from patients with melanoma is associated with tumour metastasis, and TIGIT expression on CD8+ T cells in the PBMCs from patients with gastric cancer is associated with shorter survival." (PMID 35729552, 2022). "The high proportion of TIGIT+ Tregs and a high TIGIT/CD226 ratio in Tregs in the tumor immune microenvironment were associated with poor clinical prognosis in melanoma." (PMID 35474948, 2022). "support combinatorial immunotherapy with IL-15 and TIGIT blockade to promote the NK-cell-mediated destruction of MHC class I–deficient melanoma." (PMID 35669786, 2022). "We found a significant association of TIGIT CpG5 hypomethylation and mRNA overexpression with prolonged overall survival in the TCGA cohort and progression-free survival in anti-PD-1 treated melanoma patients." (PMID 35410311, 2022). "TIGIT+ NK cells from metastatic melanoma patients displayed a lower cytolytic activity than TIGIT– NK cells against CD155+ MHC class I-deficient melanoma cells." (PMID 34367161, 2021). "The authors suggest the development of novel combinatorial immunotherapy with IL-15 and TIGIT blockade to promote NK cell-mediated destruction of MHC class I-deficient melanoma, which are refractory to CD8+ T cell-mediated immunity." (PMID 34367161, 2021). "TIGIT is an inhibitory receptor that is expressed on the surface of T cells and is associated with poor prognosis in melanoma patients." (PMID 30814637, 2019). "The potential of less studied inhibitory receptors such as TIGIT in regulating melanoma-associated CD8+ T cell responses has been outlined in two recent studies." (PMID 29033936, 2017). "Dysfunctional CD8+ T cells are characterised by expressing different inhibitory molecules, such as LAG3, PDCD1 (encoding PD-1), CXCL13, HAVCR2 (encoding Tim3), ENTPD1 (encoding CD39), CTLA4, and TIGIT, which are all less expressed in memory-like T cells in melanoma." (PMID 38893071, 2024). "TIGIT has been implicated in the development of various tumors and is correlated with poor prognostic outcomes in various cancers, including colorectal, gastric, liver, melanoma, and head and neck squamous cell carcinomas." (PMID 35770416, 2023). "In the B16 melanoma mouse model, NK cell-specific TIGIT-deficiency led to improved survival." (PMID 34367161, 2021).
melanoma (continued). "Similarly, NK cell-specific TIGIT-deficiency resulted in a greater frequency of intra-tumoral NK cells expressing CD226 in the B16 melanoma mouse model." (PMID 34367161, 2021). "TIGIT was reported to be the key checkpoint receptor associated with NK cell dysfunction and exhaustion in several tumor-bearing mouse models (including colon cancer, melanoma, breast cancer, and fibrosarcoma) and in patients with CRC." (PMID 32714324, 2020). "TIGIT+ Tregs in the TME are linked to poor clinical outcomes for patients with various malignancies, including NSCLC, melanoma, and colorectal cancer (CRC), emphasizing their role in immune suppression." (PMID 40567374, 2025). "In a preclinical study, TIGIT blockade combined with PD-1 inhibition enhanced anti-tumor responses in melanoma models." (PMID 39857682, 2025). "In melanoma, the combination of TIGIT+ NK cells with specific gut microbial profiles predicted response to checkpoint blockade, directly linking microbiota composition with NK-mediated immunotherapy outcomes." (PMID 41246357, 2025). "Overall, our study demonstrates the feasibility and safety of editing TILs by ABE and indicates that dual KO of TIM3 and TIGIT in TILs derived from both melanoma and ovarian cancer warrants further investigation for potential clinical translation." (PMID 41394272, 2025). "Blockade of T cell immunoreceptor with Ig and ITIM domains (TIGIT), also present on both NK cells and TAMs, enhances NK cell cytotoxicity against melanoma cells in vitro and reduces metastatic growth in murine melanoma models." (PMID 40948757, 2025). "Ongoing clinical trials are evaluating anti-TIGIT antibodies in melanoma patients, particularly those with high TIGIT expression, to determine their effectiveness in enhancing anti-tumor immune responses." (PMID 39857682, 2025). "Low promoter flank methylation of TIGIT was prognostic in melanoma patients treated with anti-PD-1 immunotherapy and predicted progression-free survival." (PMID 40307913, 2025). "For example, one study found that TIGIT and PD-1 co-expressed on most NY-ESO-1-specific CD8+ T cells isolated from melanoma patients, and dual blockades of TIGIT and PD-1 further increased NY-ESO-1-specific CD8+ T cell counts." (PMID 40861801, 2025). "We have further demonstrated proof-of-principle for efficient dual ABE KO of the co-inhibitory receptors TIM3 and TIGIT, which we found to be widely expressed in human melanoma and ovarian cancer-derived TILs." (PMID 41394272, 2025). "It has been shown that the interaction between TIM3 and TIGIT with their specific ligands is inhibitory to cytokine production and immunotherapy response in melanoma." (PMID 41394272, 2025). "Particularly in melanoma, human Tregs display elevated TIGIT expression and decreased CD226 expression." (PMID 39349829, 2024). "The percentage of T cells expressing TIGIT was significantly higher in melanoma, cervical, and head and neck cancer relative to RCC primary tumors." (PMID 39105820, 2024). "The upregulation of TIGIT has been reported in several types of malignancies including intestinal stomach cancer, melanoma, acute myeloid leukaemia and multiple myeloma." (PMID 38279870, 2024). "It was found that IL-15 increased the expression of TIGIT and CD226 on TiNKs, augmented NK-cell-mediated melanoma cytotoxicity in vitro, and suppressed tumor metastasis in preclinical models together with TIGIT blockade." (PMID 38229100, 2024). "TIGIT has also been well studied in melanoma and has been shown to regulate cytotoxic responses of T cells via the TIGIT-PVR pathway." (PMID 39156900, 2024). "CD155 and its receptor, TIGIT, have been shown to be highly expressed in therapy-resistant melanoma cells and interference with both is therefore considered a possible immunotherapeutic strategy." (PMID 38893071, 2024).
melanoma (continued). "Concomitant blockade of both PD-1 and TIGIT intensifies the immunological response versus melanoma, so melanoma cells’ inhibition is much more effective than the use of anti-PD-1/PD-L1 alone in melanoma patients." (PMID 38418707, 2024). "In melanoma, KLK8, TIGIT, and TRIM63 were identified as the representative three-gene classifier for melanoma molecular subtypes to predict patients’ survival risk." (PMID 38273291, 2024). "CXCL13 was found to be preferentially enriched in dysfunctional CD8+ T cells within the melanoma ecosystem, and together with TIGIT, PDCD1 and LAG3, it has been used to define the dysfunctional state of T cells." (PMID 38519500, 2024). "Studies have indicated that in vitro PD-1 blockade leads to an increase in TIGIT expression on NY-ESO-1-reactive CD8+ T cells extracted from melanoma patients." (PMID 38375475, 2024). "We found that the degree of TIGIT positivity in RCC is comparable to that in lung cancer but lower than that in melanoma, cervical, and head and neck cancers." (PMID 39105820, 2024). "In melanoma, TILs have higher TIGIT and lower DNAM-1 expression compared to peripheral blood T cells." (PMID 38893071, 2024). "TIGIT upregulation was identified in several kinds of solid tumors and leukemia, including melanoma, NSCLC, GC, AML, and multiple myeloma." (PMID 37670328, 2023). "Tiragolumab (RG6058) is another TIGIT inhibitor and is currently being used in four phase-II melanoma clinical trials in combinatorial regimens (NCT05483400, NCT05116202, NCT05060003, NCT03554083)." (PMID 37345056, 2023). "This review mainly describes the immunosuppressive mechanism of TIGIT and its role in antitumor immunity of melanoma, so as to provide new ideas and schemes for the clinical treatment of melanoma with targeted TIGIT." (PMID 37495610, 2023). "TIGIT has been shown to be upregulated in melanoma cells, which negatively affect tumor-specific CD8+T-cells via CD155 interaction." (PMID 37345056, 2023). "Indeed, TIGIT deficiency or an antibody-mediated TIGIT blockade was sufficient to reverse NK cell exhaustion in murine models of subcutaneously implanted colon cancer, breast cancer, melanoma and chemically-induced fibrosarcoma, with the consequent impairment of tumor growth." (PMID 37760586, 2023). "We have previously shown that the melanoma-cell intrinsic expression of the immune checkpoint receptor TIGIT is pharmacologically inducible by 5-aza-dC, indicating an epigenetic regulation via DNA methylation." (PMID 37259155, 2023). "In melanoma patients, Tregs that exhibit elevated levels of TIGIT expression are found to be enriched within tumor microenvironments and display a sustained immunosuppressive phenotype." (PMID 37291608, 2023). "Numerous studies have investigated the expression and prognostic significance of TIGIT in various human cancers, including melanoma, NSCLC, hepatocellular carcinoma, thyroid cancer, gastric cancer, and colorectal cancer." (PMID 37109579, 2023). "In this context, a recently reported dual inhibitor of CD47/SIRPα and TIGIT/PVR pathways merits further study for utility as an ICI in melanoma." (PMID 36768931, 2023). "TIGIT+ NK cells from melanoma patients were found to have higher lytic potential, as determined by higher levels of perforins and granzyme, but lower lytic function, resulting in lower degranulation and specific lysis." (PMID 37345049, 2023). "For example, TIGIT expression trended higher in early melanoma but was downregulated in metastatic melanoma." (PMID 37345049, 2023). "TIGIT is also co-expressed with PD-1 in circulating CD8+ T cells of metastatic melanoma cells, and their concomitant blockade enhances tumor-specific T cell proliferation, cytokine production, and degranulation." (PMID 37629138, 2023). "Studies have found that TIGIT can be detected in different stages of melanoma, which is closely related to the occurrence, development, and prognosis of melanoma." (PMID 37495610, 2023).
melanoma (continued). "Loss of CD47 in mice bearing B16 melanomas increased the abundance of TIGIT+ CD8 T cells and NK cells in the spleen while reducing CD8 T cell numbers and the percent of TIGIT+ CD8 T cells in tumors." (PMID 36768931, 2023). "Our results reconfirm a link between intestinal microbiota and response to ICI therapy in melanoma patients and furthermore point to TIGIT as a promising target for future immunotherapies." (PMID 38017389, 2023). "We investigated nine single CpG sites within the TIGIT promoter and gene body in melanomas from the TCGA cohort, isolated immune cells from peripheral blood, melanoma and melanocyte cell lines." (PMID 35410311, 2022). "TIGIT+ immune cells were found in most cases of melanomas, in which tumor infiltrating lymphocytes were present." (PMID 35410311, 2022). "CpG5 methylation correlated inversely with TIGIT mRNA expression and TIGIT+ lymphocyte infiltrates in melanoma." (PMID 35410311, 2022). "Recently, anti-TIGIT therapeutics have drawn great attention in treating colorectal cancer, breast cancer and melanoma by modulating the activities of CD8+ T cells, Tregs and NK cells." (PMID 36466840, 2022). "In melanoma patients, results show that the combined PD-1/TIGIT inhibition enhanced in the periphery and the tumor microenvironment the activity of CD8+ T cells in comparison to single inhibition." (PMID 36231109, 2022). "Remarkably, we also found a significant fraction of melanoma cells that express TIGIT protein via IHC." (PMID 35410311, 2022). "We further investigated TIGIT mRNA expression and the effect of the hypomethylating agent 5‐aza‐dC in the A375 melanoma cell line." (PMID 35410311, 2022). "In several tumors, such as melanoma, the expression levels of TIGIT in CD8+ T cells are upregulated, and the high TIGIT/DNAM1 ratio in Tregs is associated with poor prognosis following PD-1 and/or CTLA4 pathway blockade." (PMID 35037899, 2022). "Since we found TIGIT mRNA expression in CD45− cells from melanoma tissues and TIGIT protein expression in melanoma cells via IHC, we sought to analyze tumor cell-intrinsic TIGIT expression in more detail." (PMID 35410311, 2022). "Our data demonstrate an epigenetic regulation of TIGIT expression via DNA methylation within the melanoma microenvironment." (PMID 35410311, 2022). "On the protein level we expected high expression of TIGIT in immune cells in the analyzed melanoma samples and confirmed the presence of a subset of TIGIT+ TILs." (PMID 35410311, 2022). "Pharmacological demethylation of the A375 melanoma cell line led to a constitutive TIGIT expression." (PMID 35410311, 2022). "Conditional TIGIT KO in Treg cells reduces tumor growth in a melanoma mouse model, proving that the TIGIT blockade effect is also mediated by Treg cells." (PMID 35164813, 2022). "The downregulation of DNAM-1 on NK cells and cytotoxic T cells of melanoma patients suggests that TIGIT and DNAM-1 play an antagonistic role in immunosuppression during cancer." (PMID 36497240, 2022). "In melanoma patients, increased TIGIT/CD226 ratio was observed in CD4+ Tregs compared with CD4+ effector T cells and was associated with highly suppressive TME and poor clinical outcomes." (PMID 35656508, 2022). "In melanoma, NK cells with low TIGIT expression exhibited higher cytokine secretion capacity and cytotoxicity than those with high TIGIT expression." (PMID 36552960, 2022). "A previous study has also indicated that anti-PD-L1 and anti-TIGIT antibodies synergistically enhanced tumor-infiltrating lymphocyte activity in melanoma." (PMID 36675674, 2022). "In melanoma and colon cancer mouse models, anti-TIGIT therapy results in tumor regression and improved survival." (PMID 35659630, 2022). "To further reappraise our assumption of an epigenetic regulation of TIGIT expression, we performed cell culture experiments with a human melanoma cell line." (PMID 35410311, 2022).